FBP1 (fructose-bisphosphatase 1)
Diseases named in the same sentence as FBP1 in open-access papers (continued):
Sharing a sentence is not in itself a finding about the gene and the disease.
prostate carcinoma (14 papers, 2008 to 2025). A carcinoma that arises from epithelial cells of the prostate gland. "The mechanism in prostate cancer involves loss of FBP1 expression, which causes activation of the mitogen-activated protein kinase (MAPK) pathway to elicit cancer cell invasion and metastasis." (PMID 34436420, 2021). "Associations between FBP1 and -3 and clinical parameters in prostate cancer (low, high expression: for definition see text)." (PMID 19087307, 2008). "FBP1 has been found to downregulate programmed death-1ligand (PD-L1) expression at the transcriptional level in pancreatic and prostate cancer, leading to an enhancement of tumor immunity." (PMID 38349431, 2024). "We knocked down Fbp1 in PTEN-CaP8 murine prostate cancer cells and Fbp1 knockdown significantly increased Pd-l1 expression at both mRNA and protein level in these cells." (PMID 31938049, 2020). "A number of the top genes identified in this study have previously been implicated in prostate cancer development and progression, Gleason grade, metastases and biochemical recurrence; including CANT1, FBP1, RRM2, POLE2, PDE4D, and ALDH1A3." (PMID 27980733, 2016). "Moreover, FBP1 was reported to participate in epithelial mesenchymal metastasis, invasion and transition metastasis of prostate cancer cells by regulating MAPK signaling pathway." (PMID 40464853, 2025). "However, regulation of FBP1 protein expression and its exact role in prostate cancer (PCa) is largely unclear." (PMID 36237339, 2022). "Low FBP1 expression has been found in patients with postoperative recurrence of prostate cancer." (PMID 34496868, 2021). "Some studies also showed that overexpressed FBP1 in prostate cancers can be as a tumor biomarker." (PMID 30867653, 2019). "In prostate cancer (PCa), deletion of PTEN activates the PI3K/AKT pathway to promote FBP1 protein degradation through two mechanisms." (PMID 40100307, 2025). "The frequent up-regulation of FBP1 and FBP3 in urothelial and prostate carcinoma suggests that FBPs also have an important function in gene regulation of these tumors." (PMID 19087307, 2008). "There was a concomitant up-regulation of FBP1 and FBP3 in renal cell and prostate carcinomas (p < 0.001 both)." (PMID 19087307, 2008). "FBP1 gene silencing could activate the MAPK pathway and then promote cell EMT, invasion and metastasis in prostate cancer." (PMID 33836688, 2021). "In prostate cancer, c-Myc did neither correlate to pT stage, Gleason score and preoperative PSA levels nor to FBP1/FBP3 expression or Ki-67 fraction." (PMID 19087307, 2008).
clear cell renal cell carcinoma (12 papers, 2008 to 2025). "Fructose-1, 6-bisphosphatase (FBP1) is a tumor suppressor and frequently deficient in various cancers, including clear cell renal cell carcinoma (ccRCC)." (PMID 40419474, 2025). "In renal clear cell cancer the high expression of FBP1 gene was associated with enrichment of metabolic genes such as fatty acid metabolism (p < 1E−16), reactive oxygen species pathway (p = 0.015), and bile acid metabolism (p = 0.002)." (PMID 33723286, 2021). "Also, loss of FBP1 expression in renal clear cell carcinoma associates with patient prognosis." (PMID 28262837, 2017). "The strong positive correlation between FBP1 expression and c-Myc in clear cell renal cell carcinomas is perfectly in line with the well established function of FBP1 as a transcriptional activator of c-myc." (PMID 19087307, 2008). "The transcriptional regulatory ability of FBP1 was first observed in clear cell renal cell carcinoma (ccRCC) tumors, in which FBP1 levels are uniformly decreased and FBP1 re-expression inhibits tumor progression by antagonizing glycolytic flux, thereby reducing the Warburg effect." (PMID 29991493, 2018). "Interestingly, strong FBP1 and FBP3 expression was associated with c-myc up-regulation in clear cell renal cell carcinomas (p < 0.001 and 0.09 resp)." (PMID 19087307, 2008). "Specifically, FBP1 interacts directly with the HIF inhibitory domain, thereby preventing the nuclear activity of hypoxia-inducible factors (HIFs) in clear cell renal cell carcinoma." (PMID 38349431, 2024). "Further, we demonstrate a significant correlation between FBP1 and c-myc expression in clear cell renal cancer, whereas there was no such correlation in renal papillary, prostate and bladder cancer." (PMID 19087307, 2008). "However, FBP1 restrains cell proliferation, glycolysis, and the pentose phosphate pathway by inhibiting nuclear HIF function via direct interaction with the HIF inhibitory domain in clear cell renal cell carcinoma cells." (PMID 29984231, 2018).
renal carcinoma (12 papers, 2008 to 2025). A carcinoma arising from the epithelium of the renal parenchyma or the renal pelvis. "In turn, reduced FBP1 levels increases glycolysis and leads to the progression of HCCs and renal carcinomas." (PMID 40100307, 2025). "Studies have also shown that TET2 suppresses glycolytic capability in renal carcinoma by downregulating FBP1 expression." (PMID 38238754, 2024). "The high expression of GPI, FBP1, ALDOB, and SUCLA2 indicated longer OS and a low risk of developing renal cancer." (PMID 33564363, 2021). "The high expression of FBP1, ALDOB, LDHD, and SUCLA2 indicated a longer DFS and a low risk of developing renal cancer." (PMID 33564363, 2021). "Together, the observations make the case for new therapeutics in renal cancer that target various aspects of the characteristic changes in metabolism, including restoration of function of FBP1 and CPT1A." (PMID 29176561, 2017). "FBP1 is known to negatively regulate glycolysis in various cancers, and it can suppress glycolysis and cell proliferation by interacting with the hypoxia-inducible factor inhibitory domain of renal carcinoma." (PMID 38238754, 2024). "It is proved that FBP1 interacts with HIF to inhibit the function of nuclear HIF, inhibit glycolysis and pentose phosphate pathway and inhibit the proliferation of renal cancer cells." (PMID 33836688, 2021). "We found that FBP1 as well as FBP3 are more frequently expressed in prostate and bladder cancer than in renal cancer." (PMID 19087307, 2008). "Finally, we identify early dysregulated genes (e.g., FBP1, CCDC8, ECHS1, CLDN7) and pathways in renal cancer, often related to metabolism (e.g., pentose phosphate pathway)." (PMID 41188181, 2025). "FBP1, a putative tumor suppressor, has been shown previously to inhibit tumor progression by inhibiting aerobic glycolysis and reducing the Warburg effect 30 and/or antagonizing the function of HIF in renal cancer." (PMID 31938049, 2020).
diabetes (11 papers, 2013 to 2025). "An upregulation of FBPs (mainly FBP1) occurs in diabetes-susceptible obese mice, suggesting that it is important in type II diabetes mellitus (T2DM)." (PMID 38310345, 2025). "We identified a new factor which is involved in the regulation of glucose homeostasis by protein kinase CK2 by using a qRT-PCR assay with 84 diabetes-associated genes, namely fructose-1,6-bisphosphatase (FBP1)." (PMID 36613872, 2022). "Several studies in rodent models show that increased FBP1 is associated with diabetes." (PMID 29566023, 2018). "Recent work in mice has identified AMP‐dependent regulation of fructose‐1,6‐bisphosphatase 1 (FBP1) as a critical indirect anti‐hyperglycaemic target of the most widely used diabetes drug metformin." (PMID 40400417, 2025). "We observed that the diabetes-induced increase in renal gluconeogenic gene expression (Pck1 and Fbp1) was exacerbated by metformin." (PMID 27226136, 2016). "A recent study showed that metformin treatment can reduce HGP by targeting FBP1, suggesting that FBP1 may be a promising target for diabetes management." (PMID 40459008, 2025). "Malonylation of FBP1 might suppress gluconeogenesis, contributing to fasting hyperglycemia in individuals with diabetes." (PMID 41107644, 2025). "Based on these results, we propose that one of the mechanisms by which OP alleviates diabetes may be the activation of the insulin signaling pathway and the inhibition of the mRNA expression of Fbp1 in the liver of db/db mice." (PMID 34206641, 2021). "Thus, FBP1 up-regulation will aggravate the hyperglycemic situation in type 2 diabetes mellitus." (PMID 36613872, 2022). "In addition to diabetes, FBP1 was also reported to be a tumor suppressor gene." (PMID 29566023, 2018).
ovarian carcinoma (11 papers, 2021 to 2025). A malignant neoplasm originating from the surface ovarian epithelium. "Some studies have found that FBP1 can accelerate cell cycle transition and metastasis, thereby promoting the development of ovarian cancer." (PMID 40464853, 2025). "Despite the inhibitory effects of FBP1 on various tumors, it has also been shown that reduced FBP1 expression inhibits ovarian cancer formation and cisplatin resistance in vivo." (PMID 36900384, 2023). "Ovarian cancer cell lines with increased FBP1 expression were also sensitized to cisplatin-induced apoptosis." (PMID 35477823, 2022). "Previous study demonstrated that overexpression of FBP1 conferred sensitivity to cisplatin via modulating STAT3 in ovarian cancer." (PMID 36358906, 2022). "Here, we aimed to investigate the expression profile of FBP1 in ovarian cancer, the molecular mechanisms that regulate FBP1 expression and to examine how the FBP1 regulatory axis contributes to tumorigenesis and progression in ovarian cancer." (PMID 34363022, 2021). "We found that the expression of PAX8, a marker of ovarian cancer, was higher in cisplatin-resistant ovarian cancer organoids than those with cisplatin sensitivity, but FBP1 was opposite." (PMID 34363022, 2021). "To illustrate the role of FBP1 in ovarian cancer cisplatin resistance, we established 33 cisplatin-sensitive ovarian cancer organoids and 24 cisplatin-resistant ovarian cancer organoids." (PMID 34363022, 2021). "In the present study, we validated FBP1 as a negative regulator of tumor invasiveness and chemoresistance in ovarian cancer." (PMID 34363022, 2021). "The enhanced expression of FBP1 in ovarian cancer cell lines suppressed proliferation and 2-D/3-D invasion, reduced aerobic glycolysis, and sensitized cancer cells to cisplatin-induced apoptosis." (PMID 34363022, 2021). "We also evaluated the correlation between FBP1 immunostaining and the prognosis of ovarian cancer patients by survival analysis with the log-rank test." (PMID 34363022, 2021). "The FBP1 expression level was significantly lower in ovarian cancer tissue than in normal ovarian tissue in both the Bonome and TCGA cohorts." (PMID 34363022, 2021). "The colony formation assay and transwell assay showed consistent results as above, which indicating that FBP1 had a vital impact on the metastatic ability of ovarian cancer cells, which was consistent with our gene-chip results." (PMID 34363022, 2021). "In ovarian cancer, FBP1 was found to regulate proliferation, metastasis, and chemoresistance." (PMID 35477823, 2022). "Therefore, we compared the FBP1 expression level and FBP1 promoter DNA methylation levels across 47 ovarian cancer cell lines from the Cancer Cell Line Encyclopedia (CCLE)." (PMID 34363022, 2021). "Mechanistically, we demonstrated that the loss of FBP1 expression in ovarian cancer was due to C-MYC-mediated promoter hypermethylation and that enhanced FBP1 directly interacted with STAT3 to inhibit its nuclear translocation and the subsequent activation of STAT3-regulated genes." (PMID 34363022, 2021). "To identify whether FBP1 affected CSC-like property of ovarian cancer cells, we performed a sphere formation assay and analyzed the proportion of ALDH expression." (PMID 34363022, 2021). "Our results suggested that FBP1 was downregulated in ovarian cancer and that this could be related to tumor progression; therefore, next we aim to investigate the mechanisms of FBP1 downregulation in this type of cancer." (PMID 34363022, 2021). "Indeed, methylation-specific PCR analysis of ovarian tissue samples showed that compared to healthy ovarian tissue (n = 10), ovarian cancer patients (n = 10) with high C-MYC expression levels exhibited high DNA methylation of FBP1." (PMID 34363022, 2021). "Our in vivo findings indicated that the overexpression of FBP1 could exert an anti-tumor effect on ovarian cancer cells and sensitize ovarian cancer cells to cisplatin treatment both in vitro and in vivo." (PMID 34363022, 2021).
ovarian carcinoma (continued). "Next, we determined whether the introduction of STAT3 cDNA could reverse the effect of FBP1 in ovarian cancer cells." (PMID 34363022, 2021). "Immunoblotting analysis of the background expression level of FBP1 in 12 ovarian cancer cell lines showed that the expression level of FBP1 was lower in A2780 and SKOV3 cells and higher in OVCA433 and OVCA420, so these four cell lines were selected for further experiments." (PMID 34363022, 2021). "All these signs indicated that FBP1 may play a critical role in ovarian cancer cell proliferation, apoptosis, metastasis, and response to cisplatin through involvement in oxidative phosphorylation." (PMID 34363022, 2021). "Furthermore, reducing FBP1 expression in ovarian cancer cells reversed the inhibition of cell progression induced by C-MYC knockdown." (PMID 34363022, 2021). "Since FBP1 is the rate-limiting enzyme in gluconeogenesis, we suspected whether FBP1 negatively regulates cell growth by blocking glucose metabolism in ovarian cancer cells." (PMID 34363022, 2021). "We showed that FBP1 expression was significantly decreased in ovarian cancer tissues compared with normal ovarian tissues, and low-FBP1 expression predicted poor prognosis in patients with ovarian cancer." (PMID 34363022, 2021). "In addition, PET-CT analysis showed that overexpression of FBP1 significantly suppressed the glucose uptake of xenografted ovarian cancer cells in vivo and resulted in a lower SUVmax value." (PMID 34363022, 2021). "Therefore, FBP1 may warrant consideration as a predictive biomarker for the individual response of ovarian cancer patients to chemotherapy in prospective clinical studies." (PMID 34363022, 2021). "Our results demonstrate the regulatory function of C-MYC/FBP1/STAT3 signaling axis on cell proliferation, metastasis, and chemoresistance in ovarian cancer." (PMID 34363022, 2021). "We found that 63.08% (41/65) of ovarian cancer cell lines from the CCLE database harbored FBP1 promoter DNA methylation and the degree of methylation was negatively correlated with the FBP1 mRNA expression level." (PMID 34363022, 2021). "Thus, our study suggests that FBP1 may be a valuable prognostic predictor for ovarian cancer." (PMID 34363022, 2021). "In ovarian cancer, C-MYC binds to the promoter region of FBP1 and promotes its methylation." (PMID 40100307, 2025). "Additionally, FBP1 binds to STAT3, blocks the binding of STAT3 to STAT3-mediated gene promoters, inhibits glycolysis in ovarian cancer cells, and improves cisplatin resistance in ovarian cancer." (PMID 39905019, 2025). "We then studied whether there was a correlation between FBP1 protein levels, metastasis, and SUV values using preoperative PET/CT scan data and immunohistochemical staining data from 100 ovarian carcinoma patients." (PMID 34363022, 2021). "In vivo studies also confirmed the role of STAT3 in the effect of FBP1 in ovarian cancer cells with or without cisplatin treatment." (PMID 34363022, 2021). "Multivariate analysis with the Cox proportional hazards model revealed that chemotherapeutic response (HR 3.840, P = 0.000), FBP1 expression (HR 0.582, P = 0.000), and FIGO stage (HR 1.402, P = 0.028) were independent prognostic factors for OS in ovarian cancer." (PMID 34363022, 2021). "In addition, chemotherapeutic response (HR 2.481, P = 0.000), FBP1 expression (HR 0.621, P = 0.000), and FIGO stage (HR 1.693, P = 0.009) were independent prognostic factors for DFS in ovarian cancer." (PMID 34363022, 2021). "We also found a negative relationship between endogenous FBP1 and C-MYC protein levels in four ovarian cancer cell lines." (PMID 34363022, 2021).
colon cancer (10 papers, 2011 to 2025). "Here, we demonstrated that FBP1 underwent promoter CpG hypermethylation-associated silencing in human liver and colon cancer." (PMID 22039417, 2011). "However, recent research has revealed that circFNDC3B exists in colon cancer and encodes circFNDC3B-218aa, which induces FBP1 expression and inhibits the growth and metastasis of colon cancer." (PMID 39281375, 2024). "Loss of fructose-1,6-bisphosphatase (FBP1), a rate limiting enzyme in gluconeogenesis, was found to be oncogenic in various cancer cells including gastric and colon cancer cells, suggesting that modulation of gluconeogenesis also plays an equal role in tumorigenesis." (PMID 33809844, 2021). "circFNDC3B-218aa can decrease the expression of Snail to promote the antitumor effect of FBP1 in colon cancer, to suppress the proliferation, invasion, migration and EMT of colon cancer cells." (PMID 33937077, 2021). "Downregulation of FBP1 was also observed in HT29, SW480, SW620, HCT116, LoVo and RKO colon cancer cell lines when compared to human normal adult colon tissue, and this downregulation correlated well with the promoter methylation status of FBP1." (PMID 29556139, 2018). "In human colon cancer, FBP1 expression was significantly downregulated in 80% (4/5) of the colon tumour tissues when compared with adjacent non-tumour tissues." (PMID 29556139, 2018). "Although promoter methylation frequently inactivated FBP1 in human liver and colon cancer cell lines, we cannot exclude the involvement of other mechanisms responsible for the FBP1 downregulation, such as defects in histone remodeling." (PMID 22039417, 2011). "The analysis of liver and colon cancer cell lines and tissues showed that FBP1 hypermethylation was a common event in human liver and colon cancer." (PMID 22039417, 2011). "In summary, we found that FBP1 is frequently reduced by promoter hypermethylation in most liver and colon cancer cell lines and primary tumor tissues." (PMID 22039417, 2011). "Similarly, hsa_circ_0006156 from FNDC3B has been reported to inhibit Snail expression by encoding a 218aa protein, thus promoting the tumor inhibitory effect of FBP1 in colon cancer." (PMID 38802851, 2024). "Similarly, downregualtion of FBP1 was also found in 100% (6/6) human colon cancer cell lines including HT29, SW480, SW620, HCT116, LoVo and RKO when compared to human normal adult colon tissue." (PMID 22039417, 2011). "In summary, epigenetic inactivation of FBP1 is also common in human liver and colon cancer." (PMID 22039417, 2011). "In order to know whether downregulation of FBP1 should be attributed to DNA methylation, the expression of FBP1 in human liver and colon cancer cell lines before and after Aza treatment were determined by Real-Time RT-PCR." (PMID 22039417, 2011). "Mechanistically, FNDC3B‐218aa exerted its tumour suppressive effect by acting on the Snail/FBP1/EMT axis, and FNDC3B‐218aa suppressed Snail expression, subsequently upregulating FBP1 and inhibiting EMT in colon cancer cells." (PMID 37070530, 2023). "In the current study, we identified that FBP1 was frequently down-regulated in 66.7% HCC cell lines and 100% colon cancer cell lines, and in 80% primary HCCs, 100% gastric tumors and 80% colon tumors." (PMID 22039417, 2011). "Here, we investigated the expression and DNA methylation of FBP1 in primary HCC and colon tumor." (PMID 22039417, 2011). "FBP1 expression was significantly downregulated in 80% (8/10) human liver tumor tissues, 100% (5/5) in gastric and 80% (4/5) colon tumor tissues when compared with adjacent non-tumor tissues." (PMID 22039417, 2011). "PcDNA-FBP1 expressing vector was transfected into these cells, the growth speed of human liver and colon cancer cells after FBP1 overexpression was dramatically reduced in MTT cell growth assay (p<0.05), showing a growth-suppressive effect of FBP1 on cancer cells." (PMID 22039417, 2011).